CTLA4 (cytotoxic T-lymphocyte associated protein 4)
Diseases named in the same sentence as CTLA4 in open-access papers (continued):
Sharing a sentence is not in itself a finding about the gene and the disease.
retinoblastoma (4 papers, 2018 to 2026). A malignant tumor that originates in the nuclear layer of the retina. "In Singh’s study, the expression patterns of PD-1, PD-L1, and CTLA-4 proteins differed in both groups of retinoblastomas." (PMID 36132125, 2022). "The preservation of LCMV-NP396–404-specific CD8 T cells afforded by early Rb treatment was now inhibited by blocking costimulation with CTLA4-Ig." (PMID 34206262, 2021). "Differential expression pattern of PD-1, PD-L1 and CTLA-4 proteins was found in both group I (primary retinoblastoma) and group II (chemoreduced retinoblastoma) cases." (PMID 30400835, 2018). "Expression of immune markers (PD-1, PD-L1 and CTLA-4 protein) was evaluated in 75 prospective cases of primary (Group I) and 25 cases of chemoreduced (Group II) enucleated retinoblastoma specimens by immunohistochemistry." (PMID 30400835, 2018). "Tumor microenvironment of retinoblastoma showed expression of PD- L1 in primary patients and increased expression in PD-L1, CTLA-4 and PD-1 after chemotherapy." (PMID 30400835, 2018). "Therefore, we investigated the expression of PD-1, PD-L1 and CTLA-4 in primary and chemoreduced retinoblastoma to define their significance in the tumor microenvironment with patient prognosis." (PMID 30400835, 2018). "While no clear correlation was found with patient outcomes, CTLA-4 protein expression revealed a similar pattern in both primary and chemically induced retinoblastoma." (PMID 36132125, 2022).
schistosomiasis (4 papers, 2007 to 2023). An infectious disease caused by parasitic trematodes of the genus Schistosoma that colonize human blood vessels and release eggs that can cause granulomatous reactions leading to acute (swimmer's itch or acute schistosomiasis syndrome) or chronic disease. "Consistent with this hypothesis, a previous study used a similar schistosomiasis model to that employed here to demonstrate that the anti-CTLA-4 mAb facilitates host-mediated elimination of S. japonicum, but incurs an increased level of pathological damage." (PMID 31134084, 2019). "Evidence from human lymphatic filariasis, onchocerciasis and schistosomiasis records a down-modulation of immunity which is consistent with the activity of Treg-like cells, involving IL-10, TGF-β and CTLA-4 1, 46–49." (PMID 17563918, 2007).
sialadenitis (4 papers, 2015 to 2025). Sialadenitis is an infection of the salivary glands. "Sialadenitis and xerostomia also exhibit class-specific patterns: toxicities are more pronounced with anti-CTLA-4 agents and combination therapy, though our data identified nivolumab (anti-PD-1) as a key associated agent." (PMID 41221037, 2025). "CTLA4 deletion in murine Tregs resulted in sialadenitis, and PDL-1 has been reported to prevent SS development in non-diabetic obese mice." (PMID 32403289, 2020).
squamous non-small cell lung cancer (4 papers, 2017 to 2018). "Finally, a higher frequency of CTLA-4 overexpression was found in non-squamous as respect to squamous non-small cell lung cancer, and a reduced death rate was found in CTLA-4 overexpressing tumors." (PMID 29682176, 2018).
toxicity (4 papers, 2018 to 2023). The degree to which an agent can damage an organism. "Skin toxicity is the most common adverse reaction observed with epidermal growth factor receptor (EGFR) inhibitors and checkpoint inhibitors such as anti-CTLA4 agents (T-lymphocyte-associated antigen 4) and anti-PD-1 agents (programmed cell death protein-1)." (PMID 30069667, 2018). "Patients who were treated with anti-PD-1/PD-L1 and CTLA-4 mAbs and developed ICI-related lung toxicity were recruited retrospectively to study clinical, radiological, immunological and survival data." (PMID 36013328, 2022).
visceral leishmaniasis (4 papers, 2017 to 2020). A severe form of leishmaniasis characterized by irregular bouts of fever, substantial weight loss, swelling of the spleen and liver, and anemia (which may be serious). "Apoptosis is involved in periarteriolar lymphatic sheath reduction and lymphoid follicle atrophy and is associated with CTLA-4+ cell reductions in the splenic tissue of dogs with visceral leishmaniasis (VL)." (PMID 31506501, 2019). "It has been reported that CD8+ T cells from patients with visceral leishmaniasis exhibit an increased expression of the inhibitory receptors CTLA-4 and PD-1." (PMID 30510917, 2018). "In patients with visceral leishmaniasis, elevated expression of the CTLA-4 and PD-1 inhibitory receptors has been reported." (PMID 30510917, 2018).
Wiskott-Aldrich syndrome (4 papers, 2020 to 2025). Wiskott-Aldrich syndrome (WAS) is a primary immunodeficiency disease characterized by microthrombocytopenia, eczema, infections and an increased risk for autoimmune manifestations and malignancies. "SCID, CIDs, DiGeorge syndrome, Wiskott-Aldrich syndrome, Ataxia telangiectasia, Dyskeratosis congenita, ORAI-1 deficiency, CGD, X-linked Agammaglobulinemia, ALPS, STAT1 gain of function, CTLA-4 deficiency, GATA-2 deficiency, TRAPS, FMF, NEMO, TIM3, DOCK8, STAT2, STAT3, PIK3CD." (PMID 41049857, 2025). "In contrast to what is commonly described in publications on PID, our cohort included a high proportion of patients with combined deficiencies, such as Wiskott-Aldrich syndrome, activated PI3K-delta syndrome (APDS), ataxia telangiectasia, CTLA-4, or PMG3 deficiency." (PMID 37849499, 2023).
X-linked agammaglobulinemia (4 papers, 2025 to 2026). X-linked agammaglobulinemia (XLA) is a clinically variable form of isolated agammaglobulinemia, an inherited immunodeficiency disorder (see this term), and is characterized in affected males by recurrent bacterial infections during infancy. "For example, X-linked agammaglobulinemia (caused by mutations in BTK) is probably not eight times more prevalent than, e.g., the autosomal-dominant CTLA4-(haplo)insufficiency or NFKB1-(haplo)insufficiency." (PMID 41347188, 2025).
abortion (3 papers, 2019 to 2021). the ending of pregnancy by removing a fetus or embryo before it can survive outside the uterus. "T regulatory cells (T regs) in the normal decidua have been observed to express high levels of CTLA4 and, in specimens from spontaneous abortion cases, the proportion of CTLA4+ T reg cells were found to be significantly lower." (PMID 34394102, 2021). "Response levels of IDO expression by both peripheral and decidual monocytes and DCs in spontaneous abortion with CTLA-4 treatments were lower compared to a healthy pregnancy." (PMID 31057559, 2019). "Furthermore, CTLA-4 expression by T cells increased as well which was found to be significantly reduced at the MFI in abortion-prone matings." (PMID 31057559, 2019). "We observed decreased frequency and disordered function of Tim-3+CTLA-4+dCD8+ T cells in RSA patients and abortion-prone mouse models." (PMID 31138782, 2019).
acral lentiginous melanoma (3 papers, 2024 to 2025). A form of melanoma occurring most often on the plantar, palmar, subungual, and periungual skin. "Anti-PD1 and anti-CTLA4 combination therapies have been shown to be particularly beneficial for patients with BRAF-mutant acral lentiginous melanoma." (PMID 38390259, 2024). "A 64-year-old male with stage IV acral-lentiginous melanoma (distant lymph node metastases) entered a clinical trial and received anti-PD1/-CTLA4 based study medication every four weeks, following the clinical trial protocol." (PMID 41476990, 2025).
acute pancreatitis (3 papers, 2016 to 2022). An acute inflammatory process that leads to necrosis of the pancreatic parenchyma. "The study found that the co-suppressive immune checkpoint receptors CTLA-4 and PD-1 are closely related to the occurrence of acute pancreatitis." (PMID 36133806, 2022). "Boosting immunotherapy in the rhesus macaque model by combining d-1MT with anti-CTLA-4 antibodies and vaccination resulted in severe side effects including acute pancreatitis." (PMID 28066416, 2016).
alopecia (3 papers, 2017 to 2022). Hair loss usually from the scalp. "In this regard, considering the possible contribution of the autoimmune function in alopecia, genetic variant studies of CTLA4 gene have been explored in diverse populations." (PMID 32278632, 2020).
anaphylaxis (3 papers, 2019 to 2021). An acute hypersensitivity reaction that occurs from exposure to an allergen. "Immunotherapy with a-CTLA-4 and a-PD-1 caused anaphylaxis-like side effects after repeated administrations." (PMID 31462642, 2019). "Previous studies of peanut allergy mouse models show that anti-CTLA4 therapy protects mice from anaphylaxis via inhibiting the mast cell responses; this suggests a pathogenic role of CTLA-4 in food allergies." (PMID 32369940, 2020).
anterior uveitis (3 papers, 2024 to 2025). Inflammation of the iris and anterior chamber of the eye. "Anterior uveitis with CTLA-4 inhibitors is generally mild, and in these cases, discontinuation of ICI therapy or topical steroids, cycloplegics, and/or systemic corticosteroids can all be recommended." (PMID 40981113, 2025). "Compared to monotherapy via PD-1 and PD-L1 inhibitors alone, patients undergoing CTLA-4 inhibitor monotherapy developed anterior uveitis three times faster (all within 20 days in this latter cohort)." (PMID 38337852, 2024).
aseptic meningitis (3 papers, 2021 to 2025). Inflammation of the membranes surrounding the brain and spinal cord without a bacterial pathogen. "Lastly, aseptic meningitis accounts for approximately 3% of nirAEs and is more frequently associated with anti-CTLA-4 or combination (anti-PD-L1 and anti-CTLA-4) therapies." (PMID 41287707, 2025).
astrocytoma (3 papers, 2021 to 2025). "Circulating protein—(a) vitronectin discriminates LGG from HGG (Sn:98%, Sp:91%, CUS: 3, LOE: III), (b) CTLA-4 discriminates LGG from HGG, (cutoff: 220.43 pg/ml, Sn: 82%, Sp: 78%, CUS:3, LOE:III), (c) pre-operative TGF b1 predict astrocytoma (cutoff: 2.52 ng/ml, Sn: 94.9%, Sp: 100%, CUS:3, LOE:VI)." (PMID 37704931, 2023).
bladder urothelial cancer (3 papers, 2018 to 2022). "We report a similar case of acral vasculitis occurring with a combination of anti-CTLA-4 (tremelimumab) and anti-PD-L1 (durvalumab) prescribed for the management of a metastatic urothelial bladder cancer." (PMID 30446009, 2018).
bone marrow failure (3 papers, 2022 to 2024). "Neither ALPS nor LRBA deficiency are known for bone marrow failure, but in the related Tregopathy, CTLA4-haploinsufficiency, cytopenias can be due to autoimmunity, as well as to bone marrow failure." (PMID 36119097, 2022).
cancer testis (3 papers, 2013 to 2023). "Since they express large amounts of endogenous CT (cancer testis) antigens such as NY-ESO-1, we investigated the clinical activity of single agent anti-CTLA4 antibody ipilimumab in patients with advanced or metastatic synovial sarcoma." (PMID 23554566, 2013).
Candida infection (3 papers, 2013 to 2022). "Although the PD-1 pathway inhibitors tended to provide a stronger early survival benefit than anti-CTLA-4 in mice with single-hit candidiasis, improvement in 12-day mortality was comparable between the ICI treatments." (PMID 36389687, 2022). "Others additionally confirmed a mono-therapeutic benefit of CTLA-4 blockade in mice with single-hit C. albicans sepsis or secondary candidiasis after CLP." (PMID 36389687, 2022). "Spec and colleagues compared blockade of PD-1, PD-L1, and CTLA-4 inhibition in both single-hit C. albicans sepsis and secondary candidiasis after peritonitis induced by cecal ligation and puncture (CLP)." (PMID 36389687, 2022).
carcinoid (3 papers, 2019 to 2023). "Ipilimumab, a humanized monoclonal anti-CTLA-4 antibody, plus nivolumab, a PD-1 inhibitor, demonstrated an ORR of 0% in low- and intermediate-grade carcinoid tumors." (PMID 36903295, 2023). "Activation of systemic Tregs with an increase of CTLA‐4 expression was confirmed after treatment with ICI followed by disease progression, suggesting that the CTLA‐4 signaling pathway could be one of the key mechanisms of acquired resistance to PD‐1/PD‐L1 blockade therapy in carcinoid." (PMID 33300302, 2021).
chronic hepatitis (3 papers, 2017 to 2024). An active inflammatory process affecting the liver for more than six months. "MAP2K7 and MAPK14 were highly expressed in chronic hepatitis; LAT, SOS2, and BCL‐10 were highly expressed in normal tissues; PTPN6, LCK, and CTLA4 were highly expressed in CS." (PMID 30259695, 2018).
chronic myelomonocytic leukemia (3 papers, 2020 to 2021). A myelodysplastic/myeloproliferative neoplasm which is characterized by persistent monocytosis, absence of a Philadelphia chromosome and BCR/ABL fusion gene, fewer than 20 percent blasts in the bone marrow and blood, myelodysplasia, and absence of PDGFRA or PDGFRB rearrangement. "A trial which included 124 bone marrow biopsies from patients with MDS, AML and chronic myelomonocytic leukemia (CMML) showed that PD-1, PD-L1, PD-L2 and CTLA4 were upregulated in CD34+ cells." (PMID 33804850, 2021).
CMV infection (3 papers, 2018 to 2021). "In this study, we explored the association between donor SNPs of co-stimulatory genes (CTLA4, CD28, TNFSF4, and PDCD1) and the mortality, CMV infection, GVHD, and relapse of their corresponding recipients in the Taiwanese population." (PMID 34671352, 2021). "With the importance of co-stimulatory signals in the immune system and transplantation tolerance, the associations of the four co-stimulatory genes including CTLA4, TNFSF4, CD28, and PDCD1 with the mortality, relapse, CMV infection, and GVHD after HSCT were analyzed in this study." (PMID 34671352, 2021). "In this study, we investigated further whether these is an association between 34 donor SNPs in the four co-stimulatory genes (TNFSF4, CTLA4, CD28, and PDCD1) and the occurrence of adverse outcomes (mortality, relapse, CMV infection, and GVHD) for patients with AML and ALL." (PMID 34671352, 2021).
co-infection (3 papers, 2014 to 2023). "Collectively, we show that multiple immune regulatory pathways are induced in HCV/HIV coinfection including FoxP+ Tregs, PD-1, and CTLA-4 in significant association with HIV-associated CD4 T cell loss and with apparent suppression of effector T cell responses against HIV but not HCV." (PMID 25071758, 2014).
Cognitive impairment (3 papers, 2022 to 2025). Abnormal cognition is characterized by deficits in thinking, reasoning, or remembering. "Our results demonstrate that combinatorial blockade of CTLA-4 and PD-1 destabilizes neuroimmune-regulatory networks and activates microglia, contributing to long-term neurodegeneration and cognitive impairments." (PMID 40313772, 2025).
diabetic nephropathy (3 papers, 2021). "Few studies have illuminated the genetic role of T cell costimulatory molecule CD28/CD80/CTLA4 variants in diabetic kidney disease (DKD) susceptibility." (PMID 33958973, 2021).
Ebola virus disease (3 papers, 2018 to 2025). "Increased expression of CTLA-4 and PD-L1 on T cells has been associated with Ebola virus disease fatality, and polymorphisms in the CTLA-4 gene are associated with SD progression." (PMID 36961888, 2023). "This is consistent with observations in other acute infectious diseases such as Ebola, where high levels of CTLA-4 and PD-1 have been associated with high viral loads and fatal outcomes." (PMID 29555909, 2018).
eczema (3 papers, 2022 to 2025). "Symptoms in patient P49 included immune cytopenia, IBD, and eczema, and exome sequencing identified a single heterozygous truncating SNV in CTLA4 (c.442C>T, p.Gln148*; HGNC:2505)." (PMID 35743704, 2022).
encephalomyelitis (3 papers, 2021 to 2025). Inflammation of the brain and the spinal cord. "In the largest case series reporting the clinical phenotype of CTLA-4 insufficiency, neurological involvement including autoimmune encephalitis or encephalomyelitis was reported in 28% of patients." (PMID 34097529, 2021).
food allergy (3 papers, 2018 to 2023). Gastrointestinal disturbances, skin eruptions, or shock due to allergic reactions to allergens in food. "Our findings of elevated CTLA4 by wheat allergens in the AF model supports the previous findings of a pro-allergenic role of CTLA4 in food allergies." (PMID 32369940, 2020).
fungal infections (3 papers, 2016 to 2024). "Although multiple immune processes contribute to immune regulation in response to fungal infections, we focused our attention on the IL-10, PD-1, and CTLA-4 signaling pathways as individually and collectively they have proven to be of central importance to numerous immunoregulatory networks." (PMID 27973396, 2016). "Cytotoxic T lymphocyte antigen-4 (CTLA-4) and programmed cell death protein-1 (PD-1) are the central classical checkpoint inhibitory (CPI) molecules used for the control of neoplasms and some infectious diseases, including some fungal infections." (PMID 38500881, 2024).
hemophagocytic lymphohistiocytosis (3 papers, 2023 to 2025). "Hemophagocytic lymphohistiocytosis (HLH) is less common and, in contrast to other hematological irAEs, is more frequently linked to anti-CTLA4 treatment." (PMID 38611115, 2024).
herpes zoster (3 papers, 2023 to 2025). A common dermal and neurologic disorder caused by reactivation of the varicella-zoster virus that has remained dormant within dorsal root ganglia, often for decades, after the patient's initial exposure to the virus in the form of varicella (chickenpox). "Likewise, VZV-specific T cells during active herpes zoster show phenotypic alterations characterized by an increased expression of CTLA-4 and PD-1." (PMID 37880696, 2023).
hookworm infection (3 papers, 2007 to 2024). "Also, expression of CTLA-4 on these CD4+/CD25+ T-cells was not analysed and further experiments are needed to elucidate the role of this cell population during hookworm infection." (PMID 17576364, 2007).
hypoparathyroidism (3 papers, 2019 to 2024). Hypoparathyroidism is an endocrine disorder in which the parathyroid glands in the neck do not produce enough parathyroid hormone (PTH). "Here, we report a case of severe hypocalcemia due to an antibody-mediated hypoparathyroidism as an immune-related adverse event (irAE) in a patient who was treated with the anti-PD-1 antibody nivolumab and anti-CTLA-4 antibody ipilimumab." (PMID 30791949, 2019).
IgA nephropathy (3 papers, 2019 to 2022). "The CTLA-4 rs231726 gene is associated with a higher risk of developing IgA nephropathy, and the CTLA-4 rs231779 gene is associated with proteinuria, podocyte foot process effacement, and advanced mesangial proliferation." (PMID 31177287, 2019). "CTLA-4 gene polymorphisms are present in patients with IgA nephropathy, the most common autoimmune kidney disease worldwide." (PMID 31177287, 2019). "Many studies suggest that the SNPs of CTLA-4 are associated with the pathogenesis of IgA nephropathy." (PMID 31177287, 2019). "Moreover, the presence of the SNPs +49A/G and CT60 G/A within the CTLA-4 gene locus were associated with higher proteinuria (> 1 g/day) in patients with IgA nephropathy." (PMID 31177287, 2019). "They found that frequencies of the –318/C/T SNP within the CTLA-4 gene locus appreciably differ between IgA nephropathy patients and healthy controls." (PMID 31177287, 2019).
immunotoxicity (3 papers, 2020 to 2023). "Meta analysis results showed that the incidence of grade 3–4 immunotoxicity was approximately 10–24% with programmed cell death protein 1( PD-1) or cytotoxic T lymphocyte-associated antigen-4 (CTLA-4) monotherapy, and reached 59% with combined immunotherapy." (PMID 37479966, 2023). "Checkpoint inhibitors (e.g., anti-PD-1 and anti-CTLA-4 antibodies) are associated with synergistic immunotoxicity when used in combination, producing higher proportions of grade 3, 4, and even 5 adverse events compared to their use as monotherapy." (PMID 37439935, 2023).